RAC1 (Rac family small GTPase 1)
Diseases named in the same sentence as RAC1 in open-access papers (continued):
Sharing a sentence is not in itself a finding about the gene and the disease.
Hyperbilirubinemia (1 paper, 2014). An increased amount of bilirubin in the blood. "Genetic analysis of the frequency of minor allele of NOD2, CARD9, RAC1 and ATG16L1 polymorphisms in IF patients with conjugated hyperbilirubinemia (CB≥100 μmol/L)." (PMID 24465786, 2014). "Genetic analysis of the frequency of minor allele of NOD2, CARD9, RAC1 and ATG16L1 polymorphisms in IF patients with conjugated hyperbilirubinemia (CB≥50 μmol/L)." (PMID 24465786, 2014).
Hyperreflexia (1 paper, 2021). Hyperreflexia is the presence of hyperactive stretch reflexes of the muscles. "To determine whether Rac1 disruption could reduce hyperreflexia after SCI, we performed longitudinal EMG recordings to measure changes in evoked M- and H-reflex response." (PMID 33837249, 2021).
intervertebral disc degeneration (1 paper, 2024). "Expression of Rac1 had been reported in the mouse notochord and in human NP, where it had been shown to be upregulated in patients with intervertebral disc degeneration (IVDD)." (PMID 39769393, 2024).
intestinal cancer (1 paper, 2021). "To test the functional significance of Rac1b expression in intestinal tumorigenesis we generated mice carrying a novel floxed allele permitting deletion of Rac1 exon 4 (Rac1bfl) and bred these mice onto the tamoxifen-inducible VilCreERT2Apcfl/+ intestinal cancer model." (PMID 33879799, 2021).
intrauterine growth restriction (1 paper, 2021). "During intrauterine growth restriction, Rac1 and Cdc42 were positively correlated with mTOR." (PMID 34221974, 2021).
keratitis (1 paper, 2021). A corneal disease that is characterized by inflammation of the cornea. "In this regard, neither PtdSer recognition receptors (e.g., BAI-1, Tim4) nor signaling molecules (e.g., RAC-1) have been studied in the keratitis model." (PMID 34681676, 2021).
Legionella infection (1 paper, 2015). "To determine if caspase-1 is required for the dephosphorylation of cofilin in response to Legionella infection by halting the activity of kinases or promoting the activity of phosphatases that converge on cofilin, we first assessed Rac1 and Cdc42 activation." (PMID 26686473, 2015).
Lewis lung carcinoma (1 paper, 2015). "Activation of Rac1 was assayed in human umbilical vein endothelial cells (HUVEC), transendothelial passages were measured by Transwell chambers, and hematogenously metastatic mouse model was generated by intravenous injection with Lewis lung carcinoma cells (LLC)." (PMID 25991673, 2015).
lipoma (1 paper, 2019). A benign, usually painless, well-circumscribed lipomatous tumor composed of adipose tissue. "Our description of the defect in Grhl3Cre-Rac1 mutants is the first report (to our knowledge) of a mouse model of occipito-parietal encephalocele without accompanying craniofacial defects or lipoma." (PMID 31628096, 2019).
Lissencephaly (1 paper, 2019). A spectrum of malformations of cortical development caused by insufficient neuronal migration that subsumes the terms agyria, pachygyria and subcortical band heterotopia. "Given the role of Rac1 in cell migration and actin reorganization, this small GTPase has been linked to several diseases associated with brain development, such as lissencephaly and intellectual disability." (PMID 31035701, 2019).
lung adenoma (1 paper, 2015). A benign, well circumscribed epithelial neoplasm that arises from the bronchus or the lung parenchyma. "Rac1 was found to be required for K-Ras-induced lung adenoma formation in mice and a Rac1 splicing variant with increased activity, Rac1b, appears to promote tumorigenesis in this context." (PMID 26030593, 2015).
Lyme disease (1 paper, 2025). Lyme disease (named after the towns in the USA where the disease was first identified) is a bacterial infection caused by Borrelia burgdorferi. "However, no orthologs of these factors exist in B. burgdorferi, which suggests that the use of Cdc42 and Rac1 by the Lyme disease spirochete occurs through a previously undescribed mechanism." (PMID 39727396, 2025).
lymphadenitis (1 paper, 2022). Acute or chronic inflammation of one or more lymph nodes. "We have also detected protein expression of RAC1 in lymphadenitis and different clinical stages of DLBCL tissues, by immunohistochemical staining." (PMID 36552804, 2022). "Our results revealed that the expression level of RAC1 in DLBCL was higher than that in normal tissues or lymphadenitis." (PMID 36552804, 2022). "In particular, RAC1 expression level was higher in DLBCL, compared to normal lymph tissue or lymphadenitis, and more importantly it was correlated to DLBCL clinical stages." (PMID 36552804, 2022).
malignant pleural mesothelioma (1 paper, 2021). A malignant neoplasm that arises from mesothelial cells in the pleura and shows a diffuse growth pattern. "Moreover, it has been shown that both PFKFB3 ablation and inhibition with PFK158 trigger late endosome formation in malignant pleural mesothelioma by increasing the interaction of Rac1 with Rab7, where Rab7 plays an important role in the final maturation of late autophagic vacuoles." (PMID 34359849, 2021).
mediastinal tumor (1 paper, 2021). "We next sought to determine if acquisition of a RAC1 mutation resulted in dabrafenib resistance in the PDX.008.CL cells, similar to the patient’s metastatic mediastinal tumor at progression." (PMID 34638434, 2021).
metabolic syndrome (1 paper, 2020). A cluster of metabolic risk factors for CARDIOVASCULAR DISEASES and TYPE 2 DIABETES MELLITUS. "It is thought that small GTPases like Ras-related C3 botulinum toxin substrate 1 (RAC1), Ras, and RhoA play an important role in the development of metabolic syndrome (MS)." (PMID 33072455, 2020).
metastasis (1 paper, 2018). The spread or migration of cancer cells from one part of the body (where they first appeared) to another. "Association of the expression of MDM2, IGF1, STAT1, and RAC1 and clinical characteristics such as age, gender, Campanicci grade, pathological fracture, and lung metastasis was also analyzed using the Kendall's tau-b test." (PMID 29651441, 2018).
microcytic anemia (1 paper, 2013). Anemia in which the red blood cell volume is decreased. "Kalfa and colleagues previously found that mice deficient in Rac1 and Rac2 (Rac1−/−Rac2−/− mice) exhibited mild microcytic anemia with significant anisocytosis, poikilocytosis, polychromasia, and increased hypochromic cells, target cells, and fragmented erythrocytes." (PMID 23424621, 2013). "In mice, conditional disruption of Rac1 and Rac2 results in microcytic anemia characterized by gaps in the actin membrane skeleton, irregularity of the spectrin scaffold, decreased deformability, and decreased representation of essential skeletal proteins including α- and β- spectrin and adducin." (PMID 23424621, 2013).
minimal change disease (1 paper, 2017). "Aberrations in Rac1 activity are associated with human minimal change disease and idiopathic focal segmental glomerulosclerosis." (PMID 28880939, 2017).
multiple sclerosis (1 paper, 2016). A progressive autoimmune disorder affecting the central nervous system resulting in demyelination. "Thus, our findings highlight a regulatory pathway of Tiam1/Rac1 in Th17 cells and suggest that it may be a therapeutic target in multiple sclerosis." (PMID 27725632, 2016).
muscle tumors (1 paper, 2021). "Rac1 and Cdc42 are involved in myoblast transformation, and they play an important role in muscle tumors." (PMID 34221974, 2021).
necrotizing enterocolitis (1 paper, 2014). Necrotizing enterocolitis (NEC) is a devastating disease that affects mostly the intestine of premature infants. "Lastly, we examined whether there were any differences in the frequency of the polymorphisms of NOD2, CARD9, RAC1 and ATG16L1 in relation to inflammatory etiologies of IF such as in the cases with necrotizing enterocolitis (NEC)." (PMID 24465786, 2014).
neutropenia (1 paper, 2025). A decrease in the number of neutrophils found in the blood. "We attribute the lower Rac1•GTP levels to several factors, including immunosuppression, an increased population of immature neutrophils (pandemic) in some patients, and pathogen-induced depletion of neutrophils (neutropenia) in others." (PMID 40041147, 2025).
non-alcoholic steatohepatitis (1 paper, 2017). "Moreover, in a data set downloaded from the GEO database (accession code GSE63067), gene expression of Tlr4, Nox2, Rac1 and Rac2 was remarkably increased in patients with non-alcoholic steatohepatitis compared with heathy controls." (PMID 29269727, 2017).
overactive bladder (1 paper, 2025). Symptom of overactive detrusor muscle of the urinary bladder that contracts with abnormally high frequency and urgency. "Arf6 and Rac1 may be potentially involved in detrusor overactivity, bladder wall thickening and medical treatment of overactive bladder." (PMID 40332567, 2025).
pemphigus (1 paper, 2012). Pemphigus is a group of rare autoimmune diseases that cause blistering of the skin and mucous membranes (mouth, nose, throat, eyes, and genitals).This conditioncan occur at any age, but often strikes people in middle or older age. "Inhibition of Rac1 and RhoA by pemphigus autoantibodies targeting Dsg3 and Dsg1 showed disruption of cell–cell adhesion and blister formation in epidermis." (PMID 22796473, 2012).
peripheral nerve injury (1 paper, 2023). Injury to a peripheral nerve. "In conclusion, the findings of this study suggest that EA can inhibit abnormal dendritic spine remodeling in the spinal dorsal horns of rats with peripheral nerve injury through the srGAP3/Rac1 signaling pathway and increase the mechanical pain threshold." (PMID 37211600, 2023). "In addition, EA can relieve neuropathic pain by regulating the plasticity of dendritic spines in the spinal dorsal horns of rats with peripheral nerve injury, and the srGAP3/Rac1 signaling pathway plays an important role in this process." (PMID 37211600, 2023).
pheochromocytoma (1 paper, 2020). "In rat pheochromocytoma cells, we demonstrated that short interfering RNA (siRNA)-based knockdown of Rac1 inhibits hormone secretion by preventing the secretagogue-induced activation of phospholipase D1 (PLD1)." (PMID 32664294, 2020). "In this study, we further showed that the inhibition of Rac1 and Cdc42 activities in human pheochromocytomas was directly correlated to reduced expression of the GEFs ARHGEF1 and FARP1, respectively." (PMID 32664294, 2020). "For example, in pheochromocytoma, a NET arising from chromaffin cells of the adrenal medulla, we observed that the activity of Rac1 and Cdc42 was inhibited while their relative expression remained unchanged compared to non-tumor tissue." (PMID 32664294, 2020).
pneumonia (1 paper, 2022). An acute, acute and chronic, or chronic inflammation focally or diffusely affecting the lung parenchyma, caused by an infection in one or both of the lungs (by bacteria, viruses, fungi, or mycoplasma.). "Administration of liposomes containing constitutively active Rac1 into PAR2-null mice lungs rescued phagocytosis and enhanced the survival of PAR2-null mice from pneumonia." (PMID 36204227, 2022).
polycystic) ovary (1 paper, 2014). "We observed a similar combination of elevated level of intra-ovarian 17β-estradiol and down-regulation of Rac1 on polycystic ovary." (PMID 24628852, 2014). "Further, to determine whether the activity of Rac1 in terms of its phosphorylation was affected in the DHEA treated (polycystic) ovary, the phosphorylation level of Rac1 was analyzed employing immuno-blotting." (PMID 24628852, 2014). "Thus, this domain of information suggests that DHEA/polycystic ovary may adversely affect the activity of Rac1." (PMID 24628852, 2014). "Our results suggested that expression of Rac1, pRac1 and its activity were significantly reduced in the hyperandrogenized ovary with DHEA (polycystic ovary)." (PMID 24628852, 2014). "To evaluate whether DHEA can also modulate of intra-ovarian activity of Rac1, we further evaluated the activity and expression level of Vav in the ovary after DHEA treatment (polycystic ovary)." (PMID 24628852, 2014).
Polydipsia (1 paper, 2022). Excessive thirst manifested by excessive fluid intake. "Mice with distal tubule-specific deletion of Rac1 reached adulthood but showed polydipsia and polyuria with an impaired ability to concentrate urine." (PMID 36434091, 2022).
psychosis (1 paper, 2018). "In summary, the three newly identified genes (MACROD2, RAC1, and SPHK1) are related to brain functions and have plausibility for involvement in the pathophysiology of psychosis." (PMID 29695761, 2018).
pulmonary edema (1 paper, 2016). Accumulation of fluid in the lung tissues causing disturbance of the gas exchange that may lead to respiratory failure. "In ANDV-infected MECs, inhibition of β3 and Rac1 and activation of RhoA may increase the duration of pore opening and thereby diapedesis alone may trigger pulmonary edema in HPS patients." (PMID 27795403, 2016).
Pulmonary hypoplasia (1 paper, 2016). "Therefore, they concluded that sphingosine-1-phosphate 1 and Rac1 are important mediators of pulmonary hypoplasia in this model." (PMID 27159222, 2016).
radiation pneumonitis (1 paper, 2017). Inflammation of the lung due to harmful effects of ionizing or non-ionizing radiation. "Using this clinical designed protocol we found that inhibition of Rac1 signaling might mitigate acute radiation pneumonitis as observed two weeks after irradiation." (PMID 28796249, 2017).
radiation-induced brain injury (1 paper, 2016). An injury to the brain which results results from exposure to radiation. "We also found that the Rac1-MLCK signaling pathway is involved in the increased P2Y6R-mediated microglial phagocytosis observed in radiation-induced brain injury." (PMID 26099306, 2016).
RASopathies (1 paper, 2018). "Our data point to a novel aspect in the molecular pathogenesis of RASopathies as we uncovered RIT1 as regulator of cytoskeletal changes through the RHO GTPases RAC1 and CDC42 and their effector PAK1." (PMID 29734338, 2018).
rectal tumour (1 paper, 2021). "We overexpressed RAC1 and RAC1B proteins fused to the BirA ligase (and BirA-only controls) in the mouse rectal tumour cell line CMT93, treated with biotin followed by streptavidin capture and identified enriched proteins by mass spectrometry." (PMID 33879799, 2021).
respiratory failure (1 paper, 2022). The significant impairment of gas exchange within the lungs resulting in hypoxia, hypercarbia, or both, to the extent that organ tissue perfusion is severely compromised. "Failure to adjust RAC1 activity severely compromises NMJ function, causing respiratory failure in neonates and neuromuscular symptoms in adult mice." (PMID 35676269, 2022).
Rett syndrome (1 paper, 2021). A severe neurodevelopmental disorder affecting the central nervous system. "In fact, the disruption of neuronal migration and dendritic arborization resulting from Cdkl5 knockdown are rescued by wild-type Rac1 overexpression, further supporting the pathophysiological relevance of this complex interconnection in Rett syndrome." (PMID 34943902, 2021).
sarcopenia (1 paper, 2024). Progressive decline in muscle mass due to aging which results in decreased functional capacity of muscles. "Here, we found that SELENOW KO notably decreased the protein expression of CDC42 in DEX-induced sarcopenia, whereas RAC1 was down-regulated in two sarcopenia models." (PMID 39303039, 2024). "Moreover, we found that SELENOW KO down-regulated the protein level of RAC1 in skeletal muscle of sarcopenia mice." (PMID 39303039, 2024).
scleroderma (1 paper, 2014). Scleroderma is a rare autoimmune connective tissue disorder characterized by abnormal hardening of the skin and, sometimes, other organs. "In addition, activation of Rac1 mediated CTGF expression in dermal fibroblasts cultured from lesional areas of scleroderma patients." (PMID 25121739, 2014).
serous ovarian cancer (1 paper, 2018). "We analyzed RAC1 mRNA expression data for 298 Stage III primary serous ovarian cancer patient samples in TCGA using isoform analysis tools." (PMID 30261690, 2018). "Rac1 GEF and GAP regulatory factors are mutant or exhibit altered expression in ovarian serous adenocarcinoma with a frequency of 0.3–1.6% based on our analyses of 28 relevant regulatory proteins in COSMIC v86 and the cBioPortal platform for TCGA data viewing." (PMID 30261690, 2018). "Rac1 is not found mutant in the 315 serous ovarian cancer patient samples in the TCGA." (PMID 30261690, 2018).
Skin erosion (1 paper, 2017). A discontinuity of the skin exhibiting incomplete loss of the epidermis, a lesion that is moist, circumscribed, and usually depressed. "In our long-term UV-irradiation experiments, only Rac1-EKO mice developed skin erosions." (PMID 28277539, 2017).
skin squamous cell carcinoma (1 paper, 2014). A carcinoma arising from the squamous cells of the epidermis. "In samples from human skin squamous cell carcinoma (SCC), Rac1 activity was higher in cancer tissues than in normal skin and activity correlated with keratin 17 overexpression." (PMID 24962779, 2014).
soft tissue sarcoma (1 paper, 2018). A malignant neoplasm arising from muscle tissue, adipose tissue, blood vessels, fibrous tissue, or other supportive tissues excluding the bones. "We devised a strategy to test this using an siRNA screening approach in two different human soft-tissue sarcoma cell lines: RD cells which have wild-type Rho GTPases and HT-1080 cells which contain an oncogenic N92I RAC1 mutation." (PMID 29329780, 2018). "•RAC1 knockdown sensitises soft tissue sarcoma cells to ER-stress." (PMID 29329780, 2018).
streptococcal infection (1 paper, 2013). Any of the several infectious disorders caused by members of streptococcus, a genus of gram positive bacteria belonging to the family Streptococcaceae. "In the present study, it was observed that NSC23766 reduced M1 protein-induced pulmonary MPO activity by 48%, suggesting that Rac1 activity plays a significant role in neutrophil infiltration in streptococcal infections." (PMID 23951087, 2013). "Notably, administration of NSC23766 completely inhibited M1 protein-induced gene expression of CXCL1 and CXCL2 in alveolar macrophages, indicating that Rac1 activity mediates macrophage production of CXC chemokines in streptococcal infections." (PMID 23951087, 2013). "In the present study, we demonstrate for the first time that targeting Rac1 activity reduces edema formation and structural injury in the lungs of mice exposed to M1 protein, indicating that Rac1 plays a key role in controlling acute lung injury in streptococcal infections." (PMID 23951087, 2013). "However, it was found that Rac1 inhibition had no impact of Mac-1 up-regulation on neutrophils, indicating that the NSC23766-mediated reduction of neutrophil infiltration is not related to changes in neutrophil expression of Mac-1 in streptococcal infections." (PMID 23951087, 2013).
Takenouchi-Kosaki syndrome (1 paper, 2024). "Pathogenic variants in RAC1 cause the autosomal dominant inherited intellectual developmental disorder type 48 (OMIM # 617751), while heterozygous pathogenic variants in CDC42 can cause Takenouchi-Kosaki syndrome (OMIM # 616737)." (PMID 38501224, 2024).
thymoma (1 paper, 2022). A neoplasm arising from the epithelial cells of the thymus. "Down-regulation of WNT4 by shRNA induced cell death in pTECs derived from B3 thymomas and led to decreased RAC1, but not JNK protein phosphorylation." (PMID 35965500, 2022).